DDIT4 (DNA damage inducible transcript 4)
Diseases named in the same sentence as DDIT4 in open-access papers (continued):
Sharing a sentence is not in itself a finding about the gene and the disease.
tumor (continued). "ATACseq revealed putative oxi‐sensitive and tumor‐suppressing transcription factors that may regulate important mt functional genes such as the mTORC1 inhibitor, DDIT4/REDD1." (PMID 35079680, 2022). "Additionally, expression of other IRE1α/XBP1s-target genes, including XBP1s, HIF1α, DDIT4, and JMJD1A, was increased in ALDH+ cell–enriched tumor spheroids, suggesting that the UPR pathway was activated in spheroid cultures and in CSCs." (PMID 35349489, 2022). "Furthermore, expression of DDIT4 was detected at different subcellular locations including nucleus, cytoplasm, and plasma membrane in both CRC tumor cells and adjacent normal tissues by IHC analysis." (PMID 34211002, 2021). "Then, we investigated the transcript levels of DDIT4 in 89 paired tumor and adjacent noncancer control tissues from LUAD patients by RT-PCR." (PMID 34659532, 2021). "We found a significantly increased expression of DDIT3, but not DDIT4, in both canine and feline tumoral cells at 6 h post BB-CLA when compared to DMSO-treated, control tumoral cells." (PMID 29649984, 2018). "The DDIT4-mediated inhibition of the PI3K-Akt/mTOR pathway may modulate the TIME through multiple mechanisms, and a comprehensive understanding of these regulatory pathways could provide valuable insights for optimizing the precision and efficacy of tumor immunotherapy." (PMID 40900790, 2025). "Overexpression of DDIT4 and TPTEP1 in CRC patients with metastasis and advanced stages as well as in colorectal CSC-enriched spheroids indicates that increased RNA expression of these markers may be useful indicators of more aggressive tumor behavior and further disease progression in CRC patients." (PMID 34107956, 2021). "Key molecular changes included the activation of tumor-suppressing pathways and the relocalization of the mTORC1 inhibitor DDIT4/REDD1, indicating a shift toward non-oxidative energy metabolism and reduce of tumor cell growth." (PMID 38274206, 2023). "Concurrently, HIF-1 induces the expression of DDIT4/REDD1, which in a negative feedback loop impairs mTORC1, HIF-1α accumulation and suppresses tumor growth." (PMID 35406562, 2022).
cancer (109 papers, 2005 to 2026). A tumor composed of atypical neoplastic, often pleomorphic cells that invade other tissues. "Among the top four upregulated DEGs, Chil3 is linked to immune function, whereas Fn1, JamL, and Ddit4 are associated with cancer." (PMID 40206211, 2025). "Expression of DDIT4 in tumors is correlated with cancer type, but high expression is associated with worse staging in most tumors." (PMID 38507057, 2024). "Studies have shown a close association between increased DDIT4 expression in hypoxic or stressful conditions and DNA damage, inflammation, ROS, and autophagy during cancer occurrence and development." (PMID 37671155, 2023). "This association of decreased survival for high DDIT4 cohorts was observed for many other cancer types besides CESC presented in GEPIA, suggesting elevated DDIT4 is associated with poor prognosis and a vitamin D component." (PMID 35079680, 2022). "DDIT4 also known as REDD1 or RTP801, is expressed in response to diverse stress conditions and its abnormal expression is linked to cancer via the effects on PI3K/Akt/mTOR signaling." (PMID 34107956, 2021). "In-silico findings have shown high expression of DDIT4 in several cancers that is significantly associated with a worse prognosis." (PMID 34211002, 2021). "DDIT4 is induced by cellular stress conditions and regulates mTOR activity 7, and its abnormal expression has been linked to multiple diseases, including malignant tumors 16-17." (PMID 34659532, 2021). "Considering that DDIT4 is associated with a poor prognosis in various cancers including TNBC, our data highlight DDIT4 as a candidate resistance marker for oncolytic poxvirus therapy." (PMID 33075093, 2020). "Metformin treatment-associated ‘AMPK independent’ anti-cancer effects are mediated by regulated in DNA Damage-1 (REDD1; also known as DNA damage inducible transcript-4-DDIT4), Rag GTPases, and signal transducer and activator of transcription-3 (STAT3)." (PMID 31835318, 2019). "For example, baicalein upregulates DDIT4 and causes mTORC1 and growth inhibition in platinum-resistant cancer cells." (PMID 29976242, 2018). "To understand the molecular mechanism underlying GC growth regulation by DDIT4, we utilized phospho-array assays that detect 131 phosphorylation sites in 12 critical cancer signaling molecules." (PMID 29976242, 2018). "High DDIT4 expression is observed in several cancers and is linked to poor patient prognosis." (PMID 37671155, 2023). "Similarly, other studies have stated this fact that the high nuclear expression of DDIT4 protein is associated with advanced histological grade and enhances cancer proliferation and tumorigenesis." (PMID 37938616, 2023). "The DDIT4 gene encodes a protein whose main action is to inhibit mTOR under stress conditions, whilst several in vitro studies indicated that its expression favors cancer progression." (PMID 35754835, 2022). "For example, DNA damage-inducible transcript 4 (DDIT4) is highly expressed by different stresses and inhibits the mammalian target of rapamycin complex 1 (mTORC1) pathway associated with the treatment of cancer." (PMID 32098197, 2020). "Dysfunction of DDIT4 has been associated with multiple diseases, such as neurodegenerative disorders, ischemic proliferative retinopathy, preeclampsia, diabetes, and other degenerative pathologies, such as cancer." (PMID 29707520, 2018). "DDIT4 gene encodes a protein whose main action is to inhibit mTOR under stress conditions whilst several in vitro studies indicate that its expression favors cancer progression." (PMID 28484222, 2017). "Thus, in addition to PML NB-mediated nuclear retention of mTOR and inactivation of AKT, we have uncovered a novel mechanism by which PML NB loss contributes to mTOR activation in cancer via dysregulation of DDIT4 gene expression." (PMID 28332630, 2017).
cancer (continued). "Furthermore, ubiquitin remnant profiling and inducible knockdown has been employed to identify DNA damage-inducible transcript 4 (DDIT4) as a novel substrate of the ubiquitin ligase HUWE1 that has been implicated in cancer development and DNA damage response." (PMID 27379159, 2016). "Likewise, Pik3cd, involved in the immune response and in cancer is implicated in the mTOR pathway with Ddit4 (also known as Redd1) and Tsc1/2." (PMID 23927422, 2013). "Our data indicates that, under normal conditions, PML NBs play an important role in maintaining basal DDIT4 gene expression and that PML loss can lead to dysregulation of DDIT4 expression and therefore inappropriate mTOR activity that could drive cancer growth and progression." (PMID 28332630, 2017). "The overexpressed DDIT4 promotes the development of various cancers, as well as aggravates the vascular injury in inflammation response." (PMID 39762453, 2025). "It has been identified that a high expression level of DDIT4 is correlated with poor prognosis in multiple cancer types, including AML." (PMID 40621878, 2025). "In summary, the selective cytotoxicity of VCP inhibition towards cancer cells can be attributed to the disruption of proteotoxic stress mitigation pathways involving the ATF4/DDIT4 axis and hyperactive mTORC2/Akt signaling." (PMID 38218922, 2024). "The ROC curve showed that the area under the curve (AUC) of DDIT4 was 0.793, significantly greater than that of the other 3 genes, which helped distinguish between normal and cancer tissues." (PMID 38384328, 2024). "DDIT4 is also highly expressed in various cancer tissues, and the prognosis of patients with high DDIT4 expression is worse than those with low DDIT4 expression." (PMID 38507057, 2024). "DDIT4 plays a driving role in the development of several malignant tumors and it can be induced by a variety of conditions." (PMID 38507057, 2024). "In this study, we used the public database to investigate the mRNA expression and prognostic value of DDIT4 in pan-carcinoma." (PMID 38507057, 2024). "ANKRD1 shows increased expression during oxidative stress in bovine GC and DDIT4 (also called REDD1) is a regulator of caspase-2 (via the ATF4-dependent pathway) in human cancer cells." (PMID 36737804, 2023). "We use GEPIA to further determine the overall cancer survival for CESC based on DDIT4 gene expression levels." (PMID 35079680, 2022). "DNA-damage-inducible transcript 4 (DDIT4) and sulfatase 1 (SULF1) have now been shown to be associated with several types of cancer." (PMID 35155247, 2022). "DDIT4 activity supposedly enhances cancer cell resistance to mTOR inhibitors, thereby increasing cancer cells chemoresistance." (PMID 35659359, 2022). "Although DDIT4 function has been investigated extensively in the fields of cancer and autophagy, little is known about its role in skin aging." (PMID 35680564, 2022). "In line with the findings from GEPIA, our findings in MG‐63 cancer cells show that the mitochondria and their biogenic state can dictate DDIT4 cellular localization pattern and function." (PMID 35079680, 2022). "Results of the PPI network and enrichment analyses determined hub genes that a few of them including DDIT4 were involved in ‘microRNAs in cancer’, a pathway in CRC disease based on the KEGG DISEASE Database." (PMID 34211002, 2021). "According to the KEGG pathway analysis, DDIT4 was found to be related to PI3k-Akt/mTOR signaling and microRNAs in cancer pathway, as a part of CRC disease using the KEGG DISEASE Database." (PMID 34211002, 2021). "It was shown that DDIT4 over-expression provided an advantage on cancer cell survival and metastasis in hypoxic conditions through decreased energy consumption, leading to cancer progression, angiogenesis and resistance to chemotherapy or radiotherapy." (PMID 34045534, 2021). "Prominently, the previous studies have revealed that dysregulation of DDIT4 occurs in various human cancers with paradoxical roles." (PMID 34211002, 2021).
cancer (continued). "The higher expression of Ddit4 in cachectic muscle was further validated in animal models and cachectic cancer patients." (PMID 34175899, 2021). "Regarding HCC, the potential role of DDIT4 in this type of cancer, especially HBV-related HCC, remains to be determined." (PMID 34045534, 2021). "While as an oncogene, upregulation of DDIT4 contributes to reduction of apoptosis processes, promotion of proliferation, migration, and invasion of cancer cells in in-vitro and in-vivo cancer studies." (PMID 34211002, 2021). "DDIT4 is a key molecule in the signal of autophagy, and the autophagy will prevent the cancer cell for death in the harsh microenvironment." (PMID 34007269, 2021). "As expected, up-regulation of DDIT4 expression was observed in colorectal CSC-enriched spheroids compared to HT-29 cancer cells in our study." (PMID 34107956, 2021). "Construction of the protein-protein interaction network and the comparison of pathways enriched in cancer cachexia with 5 other muscle atrophy models revealed Ddit4 (DNA damage-inducible transcript 4), as a key protein in cancer cachexia." (PMID 34175899, 2021). "Results: mRNA levels of DDIT4 in HBE cells were significantly lower than in A549 and H1299 cells (P<0.05), and expression of the DDIT4 gene in cancer tissues was significantly higher than in adjacent tissues (P<0.0001)." (PMID 34659532, 2021). "Specially, bta-miR-34c and bta-miR-449b potentially regulated PYCR1 and DDIT4, which were involved in cancer progression and angiogenesis." (PMID 31772843, 2019). "Several in vivo and in vitro studies have demonstrated that DDIT4 promotes cancer progression and angiogenesis." (PMID 31772843, 2019). "All these data presented previously show that DDIT4 has a key role in different types of cancer and its aggressiveness." (PMID 29707520, 2018). "Several in vitro and in vivo works have demonstrated the ability of DDIT4 to generate resistance to cancer therapy." (PMID 29707520, 2018). "We herein report that high DDIT4 expression is related to the outcome (recurrence-free survival, time to progression and overall survival) in several cancer types." (PMID 28484222, 2017). "DDIT4 has been well-studied in cancer compared to other mRNAs and has-miR-30a-5p was with the highest degree in the ceRNA network." (PMID 28033431, 2016). "We also noted decreased HIF-1α levels and increased expression of Redd1/DDIT4, a stress-activated protein, which is down regulated in a subset of human cancers and also controls mTOR complex activity." (PMID 25867026, 2015). "Previous studies have demonstrated that baicalein inhibits cancer cell proliferation by upregulating the expression of DNA-Damage-Inducible Transcript 4 (DDIT4), which in turn suppresses the phosphoinositide 3-kinase/protein kinase B/mammalian target of rapamycin (PI3K/AKT/mTOR) signaling pathway." (PMID 41303544, 2025). "KEGG enrichment analysis showed that DDIT4 in the RNA-seq results of the 2 cell lines was enriched in 4 pathways, including microRNA in cancer, phosphoinositide 3-kinase (PI3K)-Akt signaling pathway, mammalian target of rapamycin (mTOR) signaling pathway, and autophagy-animal." (PMID 38384328, 2024). "Similarly, the significantly downregulated genes included CHAC1, SLC7A11, PYCR1, PSPH, and DDIT4, among others, with these genes being involved in iron death, cancer cell expansion, and apoptosis (15, –, 19)." (PMID 38299864, 2024). "Notably, previous studies revealed that DDIT4 has cancer stem cell (CSC) traits, which include self-renewal properties, quiescence, and dysregulated DNA repair." (PMID 37938616, 2023). "The prognostic DDIT4 gene enriched in the PI3K-Akt signaling pathway may play a crucial role in the activation of cancer." (PMID 36865386, 2023). "Ddit4 might be critical in cancer cachexia which showed a unique response to metabolic stress in the muscle, causing continued degradation of organelles and proteins." (PMID 34175899, 2021).
cancer (continued). "In-Silico evaluation has shown dysregulation in RNA expression levels of DDIT4 in several cancers which may be used as a poor prognostic factor in colon cancer." (PMID 34107956, 2021). "Paradoxically, upregulation of DDIT4 may promote cellular ferroptosis, and therefore its specific role in cancer merits further exploration." (PMID 34539740, 2021). "DDIT4 was suitable candidate gene in order to predict miRNAs in CRC because of not only its participation in the PI3K/Akt/mTOR signaling pathway but also its involvement in “miRNAs in cancer” pathway as shown by KEGG pathway analysis." (PMID 34107956, 2021). "Since earlier findings reported that inhibition of mTOR pathway is leading to enrichment of cancer stem cells, high DDIT4 expression could be related to expression of stem-cells markers." (PMID 34107956, 2021). "In this regard, the elevation of the hypoxia-responsive Ddit4 in Spalax, compared to its down-regulation in mice, should also be noted, as up-regulation of Ddit4 expression mediates mTOR inhibition and growth inhibition in cancer cells." (PMID 30621584, 2019). "Additionally, baicalein upregulates DDIT4 and inhibits mTORC1 and the proliferation of platinum-resistant cancer cells, indicating that DDIT4 expression has potential as a chemotherapeutic and chemoprevention agent." (PMID 29976242, 2018). "However, in GC, the second most common type of cancer in Asia in terms of incidence and cancer mortality, the clinical significance and biological role of DDIT4 remain to be elucidated." (PMID 29976242, 2018). "The DNA damage inducible transcript 4 (DDIT4) is induced by cellular stress conditions and regulates the mTOR activity, and also its abnormal expression has been linked to multiple diseases, including malignant tumors." (PMID 29707520, 2018). "In conclusion, DDIT4 overexpression is related with a worse outcome in several cancer types." (PMID 28484222, 2017). "Therefore, we predict that PML and DDIT4 expression should be positively correlated, where cancer cells with low PML have low DDIT4 gene expression and vice versa." (PMID 28332630, 2017). "All this data suggest a driver role for DDIT4 in the aggressiveness of cancer cells." (PMID 28484222, 2017). "Thus, these analyses suggest that PML likely plays a role in regulating DDIT4 gene expression in multiple cell types and cancers of diverse tissue origin." (PMID 28332630, 2017). "DDIT4 is a promising molecular marker for outcome in several types of cancer." (PMID 27294413, 2016). "DDIT4 has been well-studied in cancer compared to other mRNAs in the ceRNA network." (PMID 28033431, 2016). "Moreover, DNA methylation shaped by methionine metabolism has been implicated in cancer cachexia, where the methionine/SAM–DNMT3A/DNA hypomethylation–Ddit4/REDD1 axis exacerbates muscle wasting, underscoring the clinical relevance of nutritional regulation in cancer patients." (PMID 40761481, 2025). "As an oncogene, DDIT4 can cause the occurrence, and development of cancer via a link with RAS, stabilizing HIF1, and reducing apoptotic rate through increased anti-apoptotic proteins, which leads to an increase in cancer cell survival, proliferation, and migration and decreased apoptosis." (PMID 37938616, 2023). "Reportedly, the abrogation of metabolic activity triggered by the aberrant activation of the PI3K/AKT/mTOR pathway in cancer cells may result in the deregulation of genes involved in DNA damage and immune response, including DNA damage inducible transcript 4 (DDIT4)." (PMID 37391802, 2023). "The multifaceted involvement of DDIT4 in angiogenesis, cancer medication therapy, and the regulation of intricate intercellular signaling networks has led to the proposition that this molecule may possess a dualistic function in the initiation and advancement of cancer." (PMID 37938616, 2023). "In addition, DDIT4 is known to participate in a variety of cancers." (PMID 36768316, 2023).